ABCC9 (ATP binding cassette subfamily C member 9)
Description:
Subunit of ATP-sensitive potassium channels (KATP). Can form cardiac and smooth muscle-type KATP channels with KCNJ11. KCNJ11 forms the channel pore while ABCC9 is required for activation and regulation. Can form a sulfonylurea-sensitive but ATP-insensitive potassium channel with KCNJ8 (By similarity).
Synonyms: SUR2; CMD1O; ABC37; ATFB12; CANTU; IDMYS
Tractability: Small molecule: an approved drug acts on it; a high-quality ligand is known; it belongs to a druggable protein family. Antibody: its Gene Ontology location is reachable by antibodies, with high confidence; UniProt predicts a signal peptide or a membrane-spanning region; the Human Protein Atlas places it where antibodies can reach. PROTAC: a small molecule that binds it is known.
Target class: ABCC subfamily; ATP-binding cassette; Transporter; Primary active transporter
Safety:
Unwanted effects reported when the protein is acted on. In parentheses: how it was acted on, where the effect was seen, and who reports it.
abnormal pulse (activation, acute dosing; pancreas, renal, cardiovascular; source: Lynch et al. (2017))
atrioventricular block (inhibition, acute dosing; pancreas, renal, cardiovascular; source: Lynch et al. (2017))
cardiac arrhythmia (activation, acute dosing; pancreas, renal, cardiovascular; source: Lynch et al. (2017))
cardiac lesions (activation, acute dosing; pancreas, renal, cardiovascular; source: Lynch et al. (2017))
decreased blood glucose (inhibition, acute dosing; pancreas, renal, cardiovascular; source: Lynch et al. (2017))
decreased blood insulin (activation, acute dosing; pancreas, renal, cardiovascular; source: Lynch et al. (2017))
decreased blood pressure (activation, acute dosing; pancreas, renal, cardiovascular; source: Lynch et al. (2017))
decreased convulsions (activation, acute dosing; pancreas, renal, cardiovascular; source: Lynch et al. (2017))
decreased heart rate (inhibition, acute dosing; pancreas, renal, cardiovascular; source: Lynch et al. (2017))
increased blood insulin (inhibition, acute dosing; pancreas, renal, cardiovascular; source: Lynch et al. (2017))
increased heart rate (activation, acute dosing; pancreas, renal, cardiovascular; source: Lynch et al. (2017))
increased urinary sodium excretion (inhibition, acute dosing; pancreas, renal, cardiovascular; source: Lynch et al. (2017))
increased urine excretion (inhibition, acute dosing; pancreas, renal, cardiovascular; source: Lynch et al. (2017))
increased/decreased blood glucose (activation, acute dosing; pancreas, renal, cardiovascular; source: Lynch et al. (2017))
Gene: Protein-coding gene on chromosome 12 (21,797,389 to 21,942,543, reverse strand). Ensembl gene ENSG00000069431.
Subcellular location: Membrane
Subcellular location (Human Protein Atlas): Nucleoplasm; Plasma membrane
Pathways (Reactome):
Disease: Defective ABCC9 causes CMD10, ATFB12 and Cantu syndrome
Muscle contraction: Ion homeostasis
Neuronal System: ATP sensitive Potassium channels
Transport of small molecules: ABC-family protein mediated transport
Gene Ontology:
Molecular function: ATPase-coupled transmembrane transporter activity; potassium channel activity; transmembrane transporter binding; ATP-activated inward rectifier potassium channel activity; ATPase-coupled monoatomic cation transmembrane transporter activity; potassium channel activator activity; potassium channel regulator activity; sulfonylurea receptor activity; ABC-type transporter activity; ATP binding; ATP hydrolysis activity; inward rectifier potassium channel activity; protein-containing complex binding; transmembrane transporter activity
Biological process: cardiac conduction; defense response to virus; potassium ion transmembrane transport; response to ATP; monoatomic cation transmembrane transport; potassium ion import across plasma membrane; transmembrane transport; transport across blood-brain barrier; potassium ion transport
Cellular component: inward rectifying potassium channel; plasma membrane; potassium ion-transporting ATPase complex; cytoplasm; membrane; mitochondrion; sarcolemma; sarcomere
Genetic constraint (gnomAD): Loss-of-function variants: 77 observed, 166.99 expected, observed/expected ratio (o/e) 0.46, 90% interval 0.38 to 0.56. The upper end of that interval is the gene's LOEUF score, 0.56, which puts it in group 2 of 6, group 1 being the genes least tolerant of losing a copy. Missense variants: 1,013 observed, 1,839.4 expected, observed/expected ratio (o/e) 0.55, 90% interval 0.52 to 0.58. Synonymous variants: 626 observed, 653.04 expected, observed/expected ratio (o/e) 0.96, 90% interval 0.9 to 1.02.
Gene-disease validity (ClinGen):
ClinGen rates the evidence that ABCC9 causes each of these diseases.
hypertrichotic osteochondrodysplasia Cantu type (autosomal dominant): Definitive. Cantu syndrome is a rare disorder characterized by congenital hypertrichosis, osteochondrodysplasia, cardiomegaly, and dysmorphism.
dilated cardiomyopathy 1O (autosomal dominant): Limited. Any familial isolated dilated cardiomyopathy in which the cause of the disease is a mutation in the ABCC9 gene.
Brugada syndrome (autosomal dominant): Disputed. A genetically heterogeneous condition characterized by complete or incomplete right bundle branch block accompanied by ST elevation in leads V1-V3.
Homologues: Orthologues: chimpanzee ABCC9 (99% identical), dog ABCC9 (99% identical), macaque ABCC9 (98% identical), rabbit ABCC9 (97% identical), pig ABCC9 (97% identical), mouse Abcc9 (95% identical), guinea pig ABCC9 (95% identical), rat Abcc9 (94% identical), tropical clawed frog abcc9 (84% identical), zebrafish abcc9 (79% identical), Drosophila melanogaster MRP (31% identical), Drosophila melanogaster CG7627 (25% identical), and 9 more. Paralogues in human: ABCC8 (69% identical), ABCC3 (32% identical), ABCC1 (32% identical), ABCC2 (30% identical), ABCC6 (29% identical), ABCC5 (27% identical), ABCC10 (27% identical), ABCC4 (26% identical), ABCC11 (25% identical), ABCC12 (24% identical), CFTR (22% identical).
Diseases named in the same sentence as ABCC9 in open-access papers:
ABCC9 is named in the same sentence as 110 diseases in open-access papers, as found by Europe PMC text mining. Sharing a sentence is not in itself a finding about the gene and the disease. The quoted sentences say what the papers report.
Cantú syndrome (41 papers, 2014 to 2025). "Cantú syndrome (CS) is a rare autosomal dominant disorder caused by gain-of-function variants in the ABCC9 and KCNJ8 genes, which encode subunits of ATP-sensitive potassium (K_ATP) channels." (PMID 40943777, 2025). "Background/Objectives: Cantú syndrome is a rare autosomal dominant genetic disorder caused by gain-of-function variants in the ABCC9 or KCNJ8 genes." (PMID 40943777, 2025). "Prenatal follow-up confirmed the genetic diagnosis of Cantu syndrome secondary to a pathogenic mutation in the ABCC9 gene, with compatible facial features also identified on ultrasound." (PMID 40943777, 2025). "In this study, we investigated changes in the vascular endothelium in mice in which Cantú syndrome–associated Kcnj8 or Abcc9 mutations were knocked in to the endogenous loci." (PMID 39088268, 2024). "Her diagnosis remained elusive for ten years until a cardiomyopathy molecular genetic panel was obtained, which identified a pathogenic variant in the ABCC9 gene, confirming the diagnosis of Cantu syndrome." (PMID 38114927, 2023). "Cantu syndrome arises from mutations in either the ABCC9 or the KCNJ8 gene resulting in the dysregulation of the ATP-sensitive potassium channel." (PMID 38114927, 2023). "Pituitary macroadenoma has been observed in Cantu’ syndrome (C.S.), which is associated with the gain-of-function mutations of the ABCC9 and KCNJ8 genes." (PMID 37180726, 2023). "Recently, the gain-of-function mutations in ABCC9 is the most important genetic cause of Cantu syndrome, characterized by congenital hypertrichosis, osteochondroplasia, cardiomegaly, dilated vasculature, and pericardial effusion." (PMID 36704469, 2022). "We sought to systematically characterize high‐output cardiac hypertrophy in subjects with Cantu syndrome (CS), caused by gain‐of‐function variants in ABCC9, which encodes cardiovascular KATP (ATP‐sensitive potassium) channel subunits." (PMID 36515236, 2022). "The large deletion also included ABCC9 gene, and pathogenic variant in this gene is known to cause cardiomyopathy, excess hair growth, and intellectual disability named as Cantú syndrome." (PMID 36071901, 2022). "Most identified CS mutations are in ABCC9; the recently published International Cantu Syndrome Registry reports that 72 of the 74 described patients have confirmed ABCC9 variants." (PMID 34359961, 2021). "In terms of highly penetrant genetic variants, ABCC9 toxic gain-of-function mutations are linked to Cantu Syndrome, a complex phenotype that includes tortuous cerebral blood vessel patterns." (PMID 34526147, 2021). "Cantù syndrome (CS) arises from mutations in ABCC9 and KCNJ8 genes that lead to gain of function (GOF) of ATP-sensitive potassium (KATP) channels containing SUR2A and Kir6.1 subunits, respectively, of KATP channels." (PMID 33329006, 2020). "Cantú syndrome (CS) was first described in 1982, and is caused by pathogenic variants in ABCC9 and KCNJ8 encoding regulatory and pore forming subunits of ATP‐sensitive potassium (KATP) channels, respectively." (PMID 32100467, 2020). "The phenotype differs from Cantú syndrome, which is caused by gain-of-function ABCC9 mutations, reflecting the opposing consequences of KATP loss- versus gain-of-function." (PMID 31575858, 2019). "All pathogenic variants in ABCC9 reported to date in Cantú syndrome are gain-of-function missense mutations." (PMID 29327300, 2018). "In summary, we present a five-member three-generation family with Cantú syndrome due to a novel missense variant in ABCC9 gene showing full penetrance, and two family members with non-functioning pituitary adenomas." (PMID 29327300, 2018). "Following the description of activating ABCC9 mutations in Cantú syndrome, we have analyzed a family published 20 years ago by Irvine and identified a novel missense ABCC9 variant carried by the affected members." (PMID 29327300, 2018).
Cantú syndrome (continued). "rs77934287 is located on 12p12.1, a genomic region that contains the LOX-1 gene and ABCC9, a gene that has been associated with the Cantu syndrome, cardiac conduction disturbances and possibly cardiomyopathy." (PMID 29221444, 2017). "They reported a family of Cantu syndrome, which is a genetic disorder characterized by ABCC9 mutation, affecting both SUR2A and SUR2B." (PMID 27585542, 2016). "In the present work we investigated the effects of the patient-specific Cantu syndrome (CS) ABCC9 mutation SUR2[A478V] in different skeletal muscle types from SUR2wt/AV and SUR2AV/AV CS mice, in which mutation was introduced to the equivalent locus in the mouse genome." (PMID 34359961, 2021). "ABCC9 mutations are the major genetic cause of Cantu Syndrome." (PMID 32882918, 2020). "To date, 12 different mutations in ABCC9 have been identified in Cantu Syndrome." (PMID 32882918, 2020). "A striking example of a family trio-based WES approach was the identification of a nonsynonymous mutation in the ABCC9 gene that is causative of the Cantú syndrome—a dominant disorder characterized by cardiac defects, congenital hypertrichosis (abnormal hairiness), and distinctive facial features." (PMID 26747202, 2016). "Recently, dominant missense mutations have been reported in the ABC transporter gene, ABCC9 in several cases of Cantú syndrome, a form of congenital hypertrichosis segregating with osteochondrodysplasia, distinctive facial features, as well as cardiac defects." (PMID 24831815, 2014). "The ABCC9 subunit of the cardiac KATP channel regulates its inhibition by ATP, and this inhibition is decreased by Cantú syndrome ABCC9 variants, including those located in TMD2." (PMID 37239348, 2023). "For example, Cantú syndrome patients, frequently affected by PDA, have monoallelic activating mutations in ABCC9 or KCNJ8, which form KATP channels." (PMID 34350653, 2022). "ABCC9 and rarely KCNJ8 GOF genetic variants are associated with the Cantu syndrome, which often presents with the cardiac phenotype." (PMID 35495129, 2022). "Activating mutations in the ABCC9 and, less commonly, KCNJ8 genes—representing the two subunits of the ATP-sensitive potassium channel—have been linked with Cantú syndrome." (PMID 29327300, 2018). "Variants in the ABCC9 gene have been associated with DCM, Cantú syndrome, early repolarization syndrome, Brugada syndrome, myocardial infarction (MI), and atrial fibrillation." (PMID 26636822, 2015). "Furthermore, more than half of the patients with Cantu syndrome, a condition characterized by gain-of-function mutations in KCNJ8 or ABCC9, present with symptomatic PDA at birth." (PMID 39303216, 2024). "Cantú syndrome is a multisystem disorder caused by gain-of-function (GOF) mutations in KCNJ8 and ABCC9, the genes encoding the pore-forming inward rectifier Kir6.1 and regulatory sulfonylurea receptor SUR2B subunits, respectively, of vascular ATP-sensitive K+ (KATP) channels." (PMID 39088268, 2024). "Mice and humans affected by Cantu syndrome (CS), which is associated with the mutations of the KCNJ8 and ABCC9 genes encoding the Kir6.1 and SUR2 subunits, showed dysfunction of contractility throughout the intestine and death in the mice after the weaning on solid food." (PMID 37446251, 2023). "Cantu syndrome (CS) is caused by gain-of-function (GOF) mutations in pore-forming (Kir6.1, KCNJ8) and accessory (SUR2, ABCC9) ATP-sensitive potassium (KATP) channel subunits, the most common mutations being SUR2[R1154Q] and SUR2[R1154W], carried by approximately 30% of patients." (PMID 33529173, 2021). "The specific expression of KCNJ8 and ABCC9 in vascular mural cells, in particular brain PC, may suggest a role for these cells in the pathogenesis of Cantú Syndrome." (PMID 27725773, 2016). "Dramatic cardiomegaly arising from gain-of-function (GoF) mutations in the ATP-sensitive potassium (KATP) channels genes, ABCC9 and KCNJ8, is a characteristic feature of Cantú syndrome (CS)." (PMID 32865539, 2020).
dilated cardiomyopathy (10 papers, 2014 to 2025). Cardiomyopathy which is characterized by dilation and contractile dysfunction of the left and right ventricles. "A novel frameshift variant was identified in ABCC9 (dilated cardiomyopathy signaling) in Meishan pigs." (PMID 40340757, 2025). "Because pathogenic variants in ABCC9 gene had been known to cause dilated cardiomyopathy or atrial fibrillation, regular cardiac function check-up was recommended for the patient." (PMID 36071901, 2022). "Most reported pathogenic variant in ABCC9 gene was missense, and null variants had been reported to be associated with dilated cardiomyopathy." (PMID 36071901, 2022). "The loss-of-function mutations in the ABCC9 gene were associated with the Brugada syndrome, early repolarization syndrome, and dilated cardiomyopathy." (PMID 35495129, 2022). "ABCC9 LOF variants have been reported only twice in a patient with dilated cardiomyopathy and in a case of isolated atrial fibrillation." (PMID 35495129, 2022). "Mutations in ABCC9 gene can cause dilated cardiomyopathy and a genetic variant in the HRC gene has been linked to ventricular arrhythmia and sudden death in dilated cardiomyopathy." (PMID 29257745, 2017). "KATP is implicated in arrhythmia genesis, and mutations in genes coding for Kir6.2 (KCNJ11) and SUR2 (ABCC9) are linked to left ventricular hypertrophy and dilated cardiomyopathy in humans." (PMID 24477916, 2014). "The target panel sequencing identified a genetic variant in the ABCC9 gene in the exon 37 ABCC9 (NM_005,691.3):c.4570_4572delTTAinsAAAT (p.Leu1524LysfsTer5), rs869025349, classified as pathogenic and earlier reported in a family with dilated cardiomyopathy and ventricular arrhythmias." (PMID 35495129, 2022). "Moreover, ABCC9 mutations have been associated with dilated cardiomyopathy and atrial fibrillation." (PMID 37294764, 2023). "Similarly, a novel unique Meishan high-impact frameshift deletion (c.116 delT) in ABCC9, a regulatory subunit of a cardiac ATP-sensitive potassium channel dysregulated in the dilated cardiomyopathy pathway was observed." (PMID 40340757, 2025). "Genetic testing identified a likely pathogenic heterozygous ABCC9 gene variant (c.3892+2T>C), not previously associated with dilated cardiomyopathy or AF." (PMID 40923965, 2025).
cardiomyopathy (9 papers, 2017 to 2025). A disease of the heart muscle or myocardium proper. "ABCC9 loss-of-function mutations have been linked with cardiac channelopathies and cardiomyopathies." (PMID 40923965, 2025). "This novel ABCC9 variant suggests a genetic contribution to AF-induced cardiomyopathy beyond the expected course of TICM." (PMID 40923965, 2025). "A cardiomyopathy molecular studies panel was sent, and a pathogenic variant was identified in the ABCC9 gene, confirming the molecular diagnosis of autosomal dominant Cantu syndrome." (PMID 38114927, 2023). "In our cohort, three patients had variants identified in genes (ABCC9, FLNC, MYBPC3) that have associations with different cardiomyopathies and may contribute to the clinical phenotype in these families." (PMID 33302605, 2020).
Arrhythmia (7 papers, 2015 to 2026). Any cardiac rhythm other than the normal sinus rhythm. "Eight of these (50.0%) carried additional variants in other genes, including KCNJ8, SCN5A, SCN10A, ABCC9, and other genes related to inherited arrhythmias." (PMID 34222376, 2021). "The most induced genes were also ABCC9 and KCND3 (27- and 18-fold, P < 1 × 10−20), which code for sulfonylurea receptor 2 and potassium voltage-gated channel subfamily D member 3, important genes in cardiac arrhythmia." (PMID 41481712, 2026).
hypertrichosis (7 papers, 2016 to 2025). Excessive hair growth anywhere on the body. "Gain-of-function (GOF) mutations in either Kir6.1 (encoded by KCNJ8) or SUR2 (encoded by ABCC9) are causally associated with Cantu syndrome (CS), characterized by coarse facial appearance, hypertrichosis, and multiple cardiovascular abnormalities." (PMID 41448431, 2025). "We present a three-generation family with 5 affected members, with marked acromegaloid facies and prominent hypertrichosis, due to a novel missense variant in the ABCC9 gene." (PMID 29327300, 2018). "So far, no obvious differences in frequency or degree of craniofacial dysmorphology, hypertrichosis, or skin appearance depending on the site of the ABCC9 variant could be observed in CS individuals." (PMID 32100467, 2020). "We already noticed clinical overlap of ZLS and CS and found early DD, hypertrichosis, gingival enlargement, joint laxity, and hypoplasia of terminal phalanges and nails in one or several of the nine recently reported individuals with a dominant variant in ABCC9." (PMID 33594261, 2021).